SLFN13 (schlafen family member 13)
Description:
Endoribonuclease that cleaves tRNAs and rRNAs. Cleaves tRNAs 11 nucleotides from the 3'-terminus at the acceptor stem. Does not act on tRNA(Sec). Able to restrict HIV-1 virus replication; ability to inhibit HIV-1 replication is dependent on endoribonuclease activity.
Synonyms: hSLFN13; FLJ31952; SLFN10
Tractability: PROTAC: ubiquitination databases record sites on it.
Gene: Protein-coding gene on chromosome 17 (35,435,096 to 35,449,766, reverse strand). Ensembl gene ENSG00000154760.
Subcellular location: Cytoplasm
Subcellular location (Human Protein Atlas): Cytokinetic bridge
Gene Ontology:
Molecular function: RNA endonuclease activity; tRNA binding; zinc ion binding; catalytic activity
Biological process: rRNA catabolic process; tRNA decay; defense response to virus
Cellular component: cytoplasm
Genetic constraint (gnomAD): Loss-of-function variants: 44 observed, 52.2 expected, observed/expected ratio (o/e) 0.84, 90% interval 0.66 to 1.08. The upper end of that interval is the gene's LOEUF score, 1.08, which puts it in group 4 of 6, group 1 being the genes least tolerant of losing a copy. Missense variants: 881 observed, 1,056 expected, observed/expected ratio (o/e) 0.83, 90% interval 0.79 to 0.88. Synonymous variants: 339 observed, 368.73 expected, observed/expected ratio (o/e) 0.92, 90% interval 0.84 to 1.01.
Homologues: Orthologues: chimpanzee SLFN13 (99% identical), macaque SLFN13 (88% identical), mouse Slfn9 (63% identical), mouse Slfn8 (63% identical), mouse Slfn10 (62% identical), rat Slfn9 (61% identical). Paralogues in human: SLFN11 (77% identical), SLFN5 (50% identical), SLFN14 (43% identical), SLFN12 (25% identical), SLFN12L (25% identical), SLFNL1 (8% identical).
Diseases named in the same sentence as SLFN13 in open-access papers:
SLFN13 is named in the same sentence as 15 diseases in open-access papers, as found by Europe PMC text mining. Sharing a sentence is not in itself a finding about the gene and the disease. The quoted sentences say what the papers report.
lung carcinoma (4 papers, 2022 to 2023). "Further investigation revealed that Treg cells were substantially associated with lung cancer recurrence and that SLFN13 was one of the immune-related predictors of lung cancer recurrence." (PMID 36090985, 2022). "Whereas CCRL1 controlled intratumor T cell accumulation and activation in a murine mammary cancer cell line, SLFN13 was described as an immune-related biomarker that might predict tumor recurrence in lung cancer after curative resection." (PMID 37296610, 2023). "Additionally, over-expression of SLFN13 and DGKD confers poor prognosis to the lung cancer patients and the ovarian cancer." (PMID 37024523, 2023).
breast cancer (3 papers, 2023 to 2024). A primary or metastatic malignant neoplasm involving the breast. "SLFN13 has been shown to be downregulated in breast cancer, lung squamous carcinoma, prostate cancer, and rectal carcinoma." (PMID 39594803, 2024). "An analysis of “The Cancer Genome Atlas” database revealed the downregulation of SLFN13 in breast cancer, lung squamous carcinoma, prostate cancer, and rectal carcinoma, whereas the protein was upregulated in pancreatic- and renal-cell carcinoma." (PMID 37296610, 2023). "For example, SLFN5 and SLFN12 exhibit positive feedback in breast cancer, while SLFN5, SLFN11, and SLFN13 all play roles in HIV-1 regulation." (PMID 39558948, 2024).
glioma (2 papers, 2023 to 2024). A benign or malignant brain and spinal cord tumor that arises from glial cells (astrocytes, oligodendrocytes, ependymal cells). "In accordance with the mainly observed upregulation of SLFN13 during TMZ-promoted dormancy exit in our study, previous investigations revealed an increase in the gene expression with progressive glioma grade and hence with incremental aggressive properties." (PMID 37296610, 2023).
glioblastoma (1 paper, 2021). The most malignant astrocytic tumor (WHO grade IV). "In glioblastoma multiforme (GBM), high levels of all human Schlafens (SLFN5, SLFN11, SLFN12, and SLFN13) are correlated with shorter overall survival of patients." (PMID 34571887, 2021).
Insulin resistance (1 paper, 2022). Increased resistance towards insulin, that is, diminished effectiveness of insulin in reducing blood glucose levels. "Genes commonly upregulated in the IR-iPSCs when compared to each IS-iPSC group include EGR1 and MFGE8, which were previously associated with insulin resistance, as well as CD74, SEMA6B, SLFN13, TMEM151B, SLC22A17, and AGRN." (PMID 35987697, 2022).
malignant melanoma (1 paper, 2021). "Although SLFN11, SLFN12, SLFN13, and SLFN14 are expressed comparably in primary melanocytes and malignant melanoma cells, the high expression of SLFN5 in primary melanocytes is suppressed at both mRNA and protein levels in malignant melanoma cells." (PMID 34571887, 2021).
meningioma (1 paper, 2023). A generally slow growing tumor attached to the dura mater. "In the study, miR-3605-5p, miR-664b-5p, PNRC2, BTBD8, SLFN13, DGKD, NSD2, EXTL2, and BVES were closely corrected with the malignant progression of meningioma." (PMID 37024523, 2023).
stomach adenocarcinoma (1 paper, 2022). "The findings revealed that SLFN5, SLFN11, SLFN12, SLFN12L, SLFN13, and SLFN14 were expressed at higher levels in many cancers, including GC (stomach adenocarcinoma; STAD), while the SLFN14 expression levels were relatively low in all tumor and normal tissues." (PMID 36090985, 2022).
virus infections (1 paper, 2022). "Influenza A (PR8) and B (Victoria) virus infections were observed to induce SLFN13 mRNA expression in human lung adenocarcinoma A549 cells." (PMID 35216035, 2022).
cancer (4 papers, 2022 to 2024). A tumor composed of atypical neoplastic, often pleomorphic cells that invade other tissues. "Based on information from “The Cancer Genome Atlas,” the expression of SLFN13 is reduced in pulmonary squamous cell cancer and rectal cancer, but increased in pancreatic adenocarcinoma and krenal cell cancer." (PMID 39558948, 2024). "The SLFN5 and SLFN13 expressions in GC may play a significant role in cancer promotion and can be utilized to predict the GC prognosis." (PMID 36090985, 2022). "SLFN11, SLFN5, SLFN13, and SLFN12 are broadly transcribed in cancer cells, while SLFN12L, SLFN14, and SLFNL1 display reduced levels of expression." (PMID 39558948, 2024). "SLFN11, SLFN5, SLFN13, and SLFN12 exhibit a wide range of transcription levels in cancer cells, whereas SLFN12L, SLFN14 and SLFNL1 are barely expressed in cancer cell lines." (PMID 35768579, 2022). "We did not explore SLFN11 and SLFN13 involvement in TNBC cell viability since it appeared that their expressions were controlled by SLFN12; however, that does not take away from their roles as investigated by others in cancer biology." (PMID 39594803, 2024).
tumor (4 papers, 2019 to 2023). "The results showed that the high SLFN5, SLFN11, SLFN12, SLFN12L, and SLFN13 expression in GC was positively correlated with lymph node metastasis, tumor stage, and tumor grade." (PMID 36090985, 2022). "Each gene can predict tumor early recurrence from many patients, which confirmed the utility of SLFN13, RLTPR, HYDIN, MIR4500HG and TPRG1." (PMID 34395248, 2021). "In our study, CCRL1, SLFN13, SKI, Cables1, and DCHS1 were all shown to be regulated under TMZ-promoted dormancy and, besides tumor cells, to be expressed by endothelial cells and tumor-associated microglia/macrophages." (PMID 37296610, 2023). "The results demonstrated that SLFN5, SLFN11, SLFN12, SLFN12L, and SLFN13 expression in tumor tissues was significantly higher than that in normal tissues in paired, and unpaired tests, implying that they may play a role in promoting tumor progression in GC." (PMID 36090985, 2022). "And in accordance with the correlations of SKI with CCRL1 and SLFN13 found in our study, SKI was mainly postulated to exert tumor-promoting effects." (PMID 37296610, 2023). "Concerning the function of the respective markers, SLFN13, CCRL1, and SKI, especially, were shown to exert tumor-promoting effects in different malignancies." (PMID 37296610, 2023). "Based on Lasso regression analysis, the expressions of five immune-related genes, RLTPR, SLFN13, MIR4500HG, HYDIN and TPRG1 were closely correlated with tumor early recurrence." (PMID 34395248, 2021). "Five immune-related genes, SLFN13, RLTPR, HYDIN, MIR4500HG and TPRG1, were identified to be closely correlated with tumor early recurrence." (PMID 34395248, 2021). "SLFN13 is in addition to other SLFN family members a tRNAse which performs inhibition of proliferation and represents, therefore, a tumor suppressor gene." (PMID 31143370, 2019). "There was high concordance between RLTPR (AUC: 0.71, 95%CI: 0.59-0.83), SLFN13(AUC: 0.78, 95%CI: 0.67-0.89), MIR4500HG (AUC: 0.74, 95%CI: 0.62-0.85), HYDIN (AUC: 0.72, 95%CI: 0.61-0.83) and TPRG1 (AUC: 0.75, 95%CI: 0.64-0.86) abnormal expressions and tumor early recurrence." (PMID 34395248, 2021).
infection (1 paper, 2018). The state of being infected such as from the introduction of a foreign agent such as serum, vaccine, antigenic substance or organism. "Thus, it is currently tentative to conclude SLFN13 affects the infection of HIV." (PMID 29563550, 2018). "Expression of SLFN13 was not inducible by IFNɑ/β/γ treatment in 293T cells, but could be stimulated by the infection of VSV-G pseudotyped HIV-1 (HIVVSV-G)." (PMID 29563550, 2018).
SLFN13 also shares sentences with these, for which no sentence is quoted: Cirrhosis (1 paper); prostate carcinoma (1); rectal carcinoma (1).